MRE11 (MRE11 double strand break repair nuclease)
Diseases named in the same sentence as MRE11 in open-access papers (continued):
Sharing a sentence is not in itself a finding about the gene and the disease.
infection (continued). "Infection with Ad5 mutants lacking different E4 genes demonstrated that there was no degradation of MRE11 and Rad50 when cells were infected with Ad5 specifically lacking E4orf6–E1b55K." (PMID 28791251, 2017). "By quantitative PCR we determined that infection was not decreasing transcription levels of the Mre11 gene, or any other gene of the DNA sensing complex." (PMID 25340842, 2014). "Consistent with previous publications, Mre11 was not degraded during lytic infection with the BC Box virus mutant H5pm4139 (lane 5)." (PMID 24278021, 2013). "Interestingly, we report Mre11-dependent restriction of replication, indicating that Mre11 and ATM may play independent, and possibly opposing, roles during infection." (PMID 33563816, 2021). "We observed a slight reduction in Mre11 levels at later times during 7134 but not 7134R infection, indicating that ICP0 may target some other protein in the restriction pathway of which Mre11 is a component." (PMID 33563816, 2021). "Immunofluorescence analysis demonstrated that Mre11 was redistributed to co-localize with NS1 in cells with distinct MVM APAR bodies, but staining was completely undetectable in cells that represent the late stages of MVM infection, with robust and diffusely nuclear NS1 expression." (PMID 20949077, 2010). "However, no concatemers formed following infection with this mutant virus in cell lines containing any of mutant DNA ligase IV, DNA-PKcs, Nbs1, or MRE11, suggesting that these cellular proteins are all required for recognition and concatemerization of the adenoviral genome." (PMID 28791251, 2017). "Expression and steady-state levels of all analyzed cellular proteins (β-actin, USP7, Daxx, Rad50, Nbs1, Mre11, and PML) were not altered in UBM2 H5pm4250 versus WT H5pg4100 infection." (PMID 35254132, 2022). "Mre11 depletion did not totally abolish ATM activation, indicating a redundant mechanism for ATM activation in response to infection." (PMID 33563816, 2021).
breast and (2 papers, 2021 to 2024). "Here, we analyzed the impact of druggable DDR players in the response of patient-derived colorectal CSCs (CRC-SCs) to CHK1/2 inhibitor prexasertib, identifying RAD51 and MRE11 as sensitizing targets enhancing prexasertib efficacy." (PMID 33921638, 2021).
MRE11 also shares sentences with these, for which no sentence is quoted: adenocarcinoma (2 papers); Bloom syndrome (2); breast and ovarian cancer (2); Cerebellar atrophy (2); cerebellar degeneration (2); degenerative diseases (2); Werner syndrome (2); Arthritis (1); ataxia-oculomotor apraxia-1 (1); bladder (1); cervical cancer (1); childhood cancer (1); chronic hepatitis B (1); colorectal adenocarcinoma (1); endometrial tumors (1); esophageal carcinoma (1); Ewing sarcoma (1); genetic disorders (1); heart failure (1); hereditary breast and ovarian cancer syndrome (1); hereditary tumor syndromes (1); Hip dysplasia (1); Infertility (1); kidney cancer (1); latent infection (1); liver cancer (1); lung squamous cell carcinomas (1); Lynch syndrome (1); mesothelioma (1); myocardial infarction (1).
A further 20 diseases each share a sentence with MRE11 in 1 paper.